HSF1 (heat shock transcription factor 1)
Diseases named in the same sentence as HSF1 in open-access papers (continued):
Sharing a sentence is not in itself a finding about the gene and the disease.
cancer (continued). "That celastrol’s effects are not cancer cell type dependent might be explained by another suggested effect of celastrol, HSF1 activation." (PMID 24589236, 2014). "Furthermore, like Hsp90 itself, these cochaperones are often upregulated in cancer and some—though not all—are heat shock proteins, subject to an induction with the activation of HSF-1." (PMID 27721330, 2011). "Indeed, cancer cells growth and development highly depend on normal cellular functions governed by genes, which are not typical cancer related genes, and through which HSF1 can promote tumorigenesis." (PMID 24212658, 2011). "However, although the levels of HSPs (especially HSP27, HSP70 and HSP90) are elevated in different types of cancers, there is not always a correlation between HSF1 constitutive activation and HSP expression." (PMID 24212658, 2011). "Overexpression of HSF1 in non-metastatic PC-3 cells was accompanied by an upregulation of HSP27 at the protein level, but HSP70 and HSP90 were not affected, once again pointing out that the elevated expression of HSPs in cancer cells does not always depend on HSF1." (PMID 24212658, 2011). "Therefore, non-oncogenes like HSF1, whose functions are critical to cancer cells but dispensable to normal cells, can particularly be attractive as cancer drug targets." (PMID 19401686, 2009). "However, the transient increase in chaperone gene expression through HSF1 condensate formation may primarily serve as a compensatory mechanism to protect cells, rather than directly inhibiting cancer proliferation." (PMID 39757214, 2025). "Finally, studying the interactions between HSF1, HSP70, and key pathways, such as kinase activities and ATG protein expression, may provide insights into combination therapies targeting autophagy and chemoresistance in cancer treatment." (PMID 39850800, 2024). "Interestingly, HSF1 could promote tumorigenesis in cancer cells without HSR, and multiple target genes of HSF1 were identified in cancer cells but not in heat‐shock‐treated cells." (PMID 39248163, 2024). "Moreover, thrombospondin 4 (TSP-4) secreted from CAFs binds to integrin α2 to promote HSF1 phosphorylation at Ser326 to support the malignant phenotypes of gallbladder cancer cells, including cell proliferation, epithelial-mesenchymal transition (EMT) and cancer stemness." (PMID 39261452, 2024). "In addition, in cancer, many of the genes bound on chromatin by HSF1 are non-HSP genes." (PMID 32331382, 2020). "Although accumulated evidence has provided the possibility that HSF1 may be associated with cholesterol metabolism and its related human diseases, including cancer, the correlation between HSF1 and cholesterol metabolism in cancer development and progression has not yet been identified." (PMID 31540279, 2019). "This group showed that HSF1 knockdown in the A549 model did not prevent the morphological changes or enhanced migratory profile of heat-stressed cells, suggesting that HS significantly impacts cancer cell epithelial plasticity and the migratory phenotype independently of HSF1." (PMID 28241425, 2017). "Therefore, since the regulation of the major HSPs does not explain the entire range of HSF1 functions, there are questions remaining regarding an alternative mechanism for how HSF1 may be involved in cancer initiation or progression." (PMID 26359349, 2015). "Moreover, the transcription factor heat shock transcription factor 1 (HSF1) directly activated miR-135b expression and subsequently promoted HCC cell motility and invasiveness, revealing a novel mechanism for HSF1-mediated cancer progression that involves regulation by miRNA." (PMID 25537516, 2015). "Thus, the transcriptional activities of HSF1 induced by HSP90 inhibitors provide a feedback mechanism of limiting the HSP90 inhibitor's activity, and targeting HSF1 may provide a new avenue to enhance HSP90 inhibitors activity in human cancers." (PMID 23615731, 2013).
cancer (continued). "Furthermore, while the objective in cancer treatment might be to suppress the activity of HSF-1, one should probably not view all activators of HSF-1 as being detrimental in this respect." (PMID 27721330, 2011). "unveiled that CAFs lacking HSF1 failed to induce the expression of genes related to ECM organization and adhesion in cocultured cancer cells, when compared to their WT counterparts." (PMID 40457168, 2025). "One caveat to specifically targeting HSF1 PTMs is that some PTMs increase transcriptional activity while other PTM sites decrease activity, requiring specific PTM inhibitors to ensure a pro-cancer environment is not promoted with drug treatment." (PMID 39433125, 2024). "In 2016, although HSF1 has been well recognized as a driver of carcinogenesis, the involvement of HSF2 in various cancers had not yet been explored." (PMID 36430241, 2022). "The overexpression of HSP70 and HSF1 in tumors, including CLL, is not surprising, since cancer cells, characterized by higher metabolic needs and aberrantly activated signaling pathways, show a higher demand for chaperone cytoprotective functions." (PMID 34771616, 2021). "Both the HSF1- and UPRER-mediated stress signalling pathways are utilized by cancer cells to cell-non-autonomously advance neoplastic growth." (PMID 27744329, 2016). "Cell-non-autonomous stress signalling pathways mediated by HSF1 and the UPRER are used by cancer cells to propagate tumour growth." (PMID 27744329, 2016). "Interestingly, the strongest positive correlation was found between HSF1 and JUN family members in LAML, while HSPs levels were not correlated with HSF1 levels in this cancer." (PMID 36010586, 2022). "As described, the relationship between HSF1 and cancer has been studied since the first discovery; however, whether HSF2 affects cancer cell survival and other tumor characteristics had been not clearly shown." (PMID 36430241, 2022). "However, both higher levels of Pladienolide B and SF3B1 siRNA knockdown also change the concentration of HSF1, a form of HSR regulation that has not been previously documented during normal physiology but is observed in some forms of cancer." (PMID 28445500, 2017). "Unlike HSF1, the PI3K-AKT pathway has been known to play a role in cancer for many years." (PMID 29088759, 2017). "Because CA mediated HSF1 and HSP70 upregulation, we speculate that it did not affect cancer cell proliferation or growth." (PMID 26029925, 2015). "However, compared with HSF1, HSF2 has not been extensively investigated in cancer, and its function and molecular mechanisms in oncogenesis are largely unknown." (PMID 34917120, 2021). "In addition to its role in stress responses, HSF1 can also activate the expression of non-HSP genes in tumor cells, thereby regulating cell cycle progression, promoting epithelial–mesenchymal transition (EMT), and maintaining the stability of cancer stem cell populations." (PMID 39682216, 2024).
tumor (262 papers, 2009 to 2026). "HSF1 also plays multifaceted roles in tumor-associated processes including proliferation and metastasis." (PMID 41028522, 2025). "Mounting evidence has revealed that HSF1 plays multifaceted roles in tumor-associated cellular processes including cell proliferation, tumor microenvironment (TME) remodeling, chemoresistance and metastasis." (PMID 41028522, 2025). "HSF1, a vital regulator of the heat shock response, has been implicated in tumor malignancy and poor prognosis." (PMID 40722679, 2025). "The increased HSF1 concentrations are associated with poor prognosis, larger tumor size and shorter overall and disease-free survival." (PMID 40287736, 2025). "The critical phosphorylation site for HSF1 activation is on Ser326 (pHSF1), which serves as a functional hallmark for the tumor-promoting HSR." (PMID 40204953, 2025). "HSF1 is linked to tumorigenesis, as demonstrated by marked suppression of tumor occurrence in mouse carcinogenesis models where HSF1 expression was disrupted." (PMID 40457168, 2025). "Participation of HSF1 in the maintenance of tumor growth is also associated with its ability to regulate diverse processes critical for tumor cells, including proliferation, cell death, and drug resistance by diverse mechanisms." (PMID 39682216, 2024). "High levels of HSF1 expression are associated with M2 macrophage infiltration, can promote tumor proliferation, and are linked to poor prognosis." (PMID 39678502, 2024). "A pioneering work performed in skin carcinogenesis mouse models shows reduced oncogenic Ras-induced tumor formation upon the loss of Hsf1." (PMID 39850800, 2024). "This correlated with HSF1’s crucial role in maintaining the genome integrity as a part of the PSR, contributing to BRCA-mutated tumor cells' addiction to HSF1." (PMID 39850800, 2024). "KRIBB11 has abolishing activity on the heat shock-dependent induction of Hsp70 gene through inhibition of HSF1, causing significant decrease of tumor growth." (PMID 38589452, 2024). "Mounting evidence has suggested that HSF1 plays multifaceted roles in various cellular responses associated with tumorigenesis, such as the alteration of the tumor microenvironment, genome repair, among other critical cellular response pathways." (PMID 37153737, 2023). "We show that targeting the DYRK2-HSF1 axis induces death in proteasome inhibitor-resistant cells and that dual loss of DYRK2 and HSF1 is indeed additive toward reducing TNBC tumour burden in ectopic and orthotopic xenograft models." (PMID 36622366, 2023). "While the positive effects of HSF1 on growth and longevity are generally beneficial, increased HSF1 activity is also linked to increased tumor incidence in mice and humans." (PMID 38164224, 2023). "While AKT1, mTORC1, MEK1, p38 and DYRK2 can all activate HSF1, the current study indicates that activity of only AKT1 and mTORC1 maintains a strong association with HSF1 activity in tumours." (PMID 35080342, 2022). "Both HSF1 and HSPs are implicated in oncogenesis and responsible for the tumor resistance to chemo- and radiotherapy." (PMID 33806538, 2021). "We further show that in clinical TNBC samples DYRK2 protein levels correlate with active HSF1, and are associated with high rates of tumour recurrence and poorer patient survival." (PMID 33268814, 2021).
tumor (continued). "The critical phosphorylation site for HSF1 activation is residue Ser326, which serves as functional hallmark of the tumor-promoting HSR response." (PMID 34188043, 2021). "HSF1 activation in multiple cancers is significantly associated with tumor metastasis and death and mTOR is essential for HSF1 activation and HSP90 synthesis." (PMID 33946531, 2021). "This phenomenon also suggests that HSF1 is associated with a variety of biological functions in promoting tumor progression." (PMID 34064083, 2021). "Given the difficulty of modeling recurrence with experimental tumor models, the importance of HSF1 to tumor recurrence can currently be at best inferred from its association with the CSC phenotype in the tumor cell population." (PMID 32331382, 2020). "These overall results remained rather stable after adjustment for confounders and interaction by tumor stage, which supports a causal relationship that cannot be explained by tumor stage, HSF1 expression, or by the assessed confounders." (PMID 31699156, 2019). "Here, we show that CNAs of 8q24.3 genes, including HSF1, are tightly linked to 8q24.3 copy number in tumor patients and can affect patient outcome." (PMID 31699156, 2019). "Collectively, these findings together suggested that FAM3C likely initiates the crosstalks among YY1, HSF1 and Akt, finally causing excessive Akt activation to trigger tumour growth and invasion." (PMID 30887707, 2019). "HSF1 governs the function of more than 1000 genes, some of which are functionally linked to tumor progression." (PMID 29930764, 2018). "CBL0137 treatment by ILP reduces SSRP1 expression, suppresses HSF1/hsp70 transcription, and causes tumor cell death, and its efficacy can be improved by hyperthermia." (PMID 30581774, 2018). "High levels of HSF1 activation in tumour cells have been associated with increased cell growth and metastasis." (PMID 29247221, 2017). "HSF-1 has been found to be associated with several oncogenic pathways that have important roles in maintaining tumor development." (PMID 29348836, 2017). "The rank analysis discovers the association between HSF1 and HSF1-CanSig genes encoded in chromosome 8q in 27 primary tumor sites." (PMID 29268782, 2017). "In ESCC patients, the HSF1 expression in tumor or in stromal cells was significantly associated with tumor stage, lymph node metastasis and clinical stage." (PMID 26511079, 2015). "Inhibition of heat shock protein 90 (Hsp90) is known to induce the heat shock response via activation of HSF1 which is associated with tumor development, metastasis and therapy resistance and also with an increased susceptibility to NK cell-mediated lysis." (PMID 25854583, 2015). "The HSF1 expression level in tumor cells was positively associated with the HSF1 expression level in stromal cells (P < 0.001, R = 0.706)." (PMID 26511079, 2015). "In mice and in cell culture, genetic ablation of hsf1 expression potently impairs tumorigenesis and cellular transformation driven by oncogenic activation or tumor suppressor loss." (PMID 26359349, 2015). "Why does the expression of HSF1 in tumor cells and in stromal cells show different associations with ESCC?" (PMID 26511079, 2015). "In this study, the level of HSF1 expression in tumor cells was positively associated with the HSF1 level in stromal cells." (PMID 26511079, 2015). "HSF1 is able to associate with cell cycle regulators cdc20 and polo-like protein kinase 1, participating in the regulation of tumor cell chromosomal stability." (PMID 25199534, 2014). "A simple loss of the NF1 tumor suppressor followed by elevated RAS/MAPK signaling leads to HSF1 activation via phosphorylation of Ser326." (PMID 24467529, 2014).
tumor (continued). "Stimulating mTORC1 in these HSF1-deficient cells drives catastrophic proteomic imbalance, triggering pronounced cell death, in part through unchecked amyloidogenesis, and suppressing tumor growth in vivo." (PMID 41835397, 2026). "Moreover, pathways associated with stress response, such as Hsf2 target genes, Hsf1 activation, and response to heat, also exhibited significant downregulation in tumor tissues." (PMID 41186645, 2026). "In addition, in the M2a state, MAF bZIP transcription factor B (MAFB) and heat shock transcription factor 1 (HSF1) TFs, whose elevated expression in TAMs associates with more aggressive tumor growth, had significantly upregulated phosphosites." (PMID 41255709, 2025). "Previous studies have implicated this residue in tumor-related functions of HSF1, suggesting that the loss of SUMOylation could have broader implications beyond stress adaptation." (PMID 40617887, 2025). "As a transcription factor, HSF1 can cause structural and functional remodeling of the tumor stroma." (PMID 40399470, 2025). "In tumor immunity, HSF1 inhibition triggers loss of NK cell activation ligand MICA/B." (PMID 38743344, 2024). "Indeed, protein levels of DYRK2 positively correlate with active HSF1 levels in TNBC patient tumours and together associates with poor outcome." (PMID 36622366, 2023). "Recent studies have demonstrated that HSF1 expression is negatively correlated with immune checkpoint genes’ expression, tumor mutational burden (TMB), and microsatellite instability (MSI) in CRC, implying no reaction to immunotherapy when HSF1 is highly expressed." (PMID 36010849, 2022). "Other tumor-infiltrating cells, such as tumor-associated macrophages (TAMs), may also be dependent on HSF1 activity to maintain high levels of HSPs, whereby Hsp72 was shown to be important for TAM infiltration of tumors." (PMID 32331382, 2020). "For instance, in tumor cells constantly experiencing the pressure of stressful factors, heat shock factor 1 (HSF1), a transcriptional activator, causes the enhancement of heat shock protein synthesis, which protects the cells from future stronger insults and increases their survival." (PMID 32456366, 2020). "However, the precise molecular mechanisms by which increased and activated HSF1 via RAS-MAPK signaling causes tumor development and progression is still poorly understood." (PMID 31540279, 2019). "Moreover, HSF1 expression in stromal cells was associated with advanced tumour stage, lymph node metastasis and clinical stage, and poor outcome of ESCC." (PMID 30326922, 2018). "HSF-1 is able to associate with cell cycle regulators and modulate the metabolism of glucose and lipids by indirectly regulating insulin receptor protein expression, which has been demonstrated to be important for tumor initiation and development." (PMID 29348836, 2017). "In contrast, Ras activation induces HSF1 and loss of HSF1 delays tumor formation." (PMID 26320184, 2015). "Furthermore, the high level of HSF1 expression in both tumor cells and stromal cells was significantly associated with worse DFS and OS of ESCC patients." (PMID 26511079, 2015). "Both age-dependent collapse of cell proteostasis and tumour-associated increase of protein misfolding are events regulated by HSF1, strengthening the evidence of the unique role of this protein in preventing global instability of proteome in several pathophysiological conditions." (PMID 24213118, 2011).